FASN (fatty acid synthase)
Diseases named in the same sentence as FASN in open-access papers (continued):
Sharing a sentence is not in itself a finding about the gene and the disease.
cancer (continued). "In addition, some studies show a relationship between mutations in the FASN enzyme and cancer incidence." (PMID 24829560, 2014). "Some researchers claim that the inhibition of FASN will reduce the formation of essential fatty acid that is needed for the growth of cell membrane and for energy supply, which may be the cause of cancer cell apoptosis." (PMID 24778702, 2014). "Blocking FASN activity causes cytotoxicity in human cancer cells overexpressing FASN." (PMID 22177475, 2011). "Among the proteins found to be downregulated in N130-induced cells, we selected fatty acid synthase (FASN) for further characterization because it has been shown to be associated with tumor progression in a variety of human cancers and its inhibitors are available for potential translation studies." (PMID 20508725, 2010). "The relationship between ATF6-high and FASN-high individuals is evident through their association classified as co-occurrence, despite not reaching significance in the TCGA database (P = 0.297), likely due to lower case numbers compared to the Pan-Cancer Atlas database (P < 0.001)." (PMID 40890536, 2025). "Furthermore, high levels of FASN expression may confer a survival advantage for cancer cells and associate with poor prognosis and disease recurrence." (PMID 38467328, 2024). "To identify cancer cell dependencies similar to the consequence of depleting FASN expression that may underlie the reduced metabolic fitness and increased susceptibility to killing by cytotoxic T cells, we analyzed CRISPR-based gene effects identified in the Cancer Cell Line Encyclopedia (CCLE)." (PMID 39349429, 2024). "Studies have shown that inhibition of FASN can effectively and extensively inhibit the DNA replication of cancer cells and delay the S phase transition in the cell cycle, suggesting that the pathway of fatty acid synthesis is associated with the growth of cancer cells." (PMID 37696831, 2023). "In addition, oleuropein may change the activity of critical molecules implicated in the initiation and progression of cancer, including MAPKs, the c-Met proto-oncogene, and the fatty acid synthase (FASN) enzyme." (PMID 35903701, 2022). "Moreover, cytosolic citrate is obligatory for the promotion of cancer cell growth and proliferation, thus supporting our results that a decrease in FASN expression and the level of citrate are associated with less proliferative properties of intestinal adenomas and an increase of survival of mice." (PMID 35742953, 2022). "Ole’s anti-cancer benefits could be attributed to its capacity to inhibit the fatty acid synthase enzyme (FASN), which could be linked to the fact that Ole modifies gene expression and enzymatic activity of this enzyme, as seen in colon cancer cell lines SW620 and HT-29 in vitro." (PMID 36013319, 2022). "In addition to EGFR mutated cancer cells, Akt pathway was related to chemoresistance in FASN-overexpressed gastrointestinal stromal tumors (GISTs) with KIT mutated and the activation of oncogenic pathway like PI3K/AKT/mTOR pathway promoted chemoresistance to imatinib." (PMID 35646898, 2022). "However, cancer researchers have long hypothesized that the lipid deficiency caused by FASN inhibition can be circumvented by increasing the uptake of exogenous lipids from the host, which would confer resistance to FASN inhibitors." (PMID 33928023, 2021). "Thus, the hyper-palmitoylation in TEAD-YAP/TAZ may be one of the mechanisms underlying the overexpressed FASN and activated lipid metabolism in many cancers." (PMID 34803494, 2021). "For example, high levels of fatty acid synthase (FASN) expression have been associated with invasive tumor phenotypes, while both acetyl-CoA carboxylase and FASN have been shown to be highly expressed in malignant tumors and are also indicators of poor prognosis." (PMID 33014877, 2020).
cancer (continued). "However, progress to the clinic of FASN inhibitor drugs has been hampered by poor pharmacokinetics and associated side effects, particularly weight loss and anorexia, which limit their potential for the treatment of patients with cancer." (PMID 33083663, 2020). "In addition, several genetic changes in FASN gene have been associated with cancer prognosis." (PMID 33194695, 2020). "However, a little-known fact about the anti-cancer effects of fenofibrate in inhibiting FASN and the molecular mechanisms underlying the FASN inhibition relationship on cell death remain unclear." (PMID 30824767, 2019). "Therefore, fatty acid synthase is associated with poor prognosis in patients with cancer." (PMID 30717356, 2019). "Moreover, it is eminent that higher level of FASN may regulate oncogenic proteins associated with malignant transformation, suggesting its important role in the progression of cancer." (PMID 31030489, 2019). "Fatty acid synthase (FASN) is a key enzyme for endogenous lipogenesis that can promote the synthesis of long-chain fatty acids, and recent studies have shown that FASN may be associated with the metastasis of cancer cells." (PMID 27813492, 2016). "In an effort to repurpose US FDA-approved drugs targeting FASN, proton pump inhibitors (PPIs) were found to effectively inhibit FASN by targeting its thioesterase domain and inhibit cancer cell proliferation." (PMID 41158759, 2026). "In cancer, dysregulated lipid metabolism, particularly the overactivity of fatty acid synthesis pathways such as fatty acid synthase (FASN), promotes rapid proliferation and survival of tumor cells under adverse conditions." (PMID 41459114, 2026). "In this study, we investigated the differences in FASN expression among cancer, adjacent, and normal tissues and explored the possible influencing factors." (PMID 40995612, 2025). "In pancreatic cancer, high expression of circ_0018909 can promote EMT by inducing polarization of M2-type macrophages and regulating miR-545-3p to promote FASN expression, which affects cancer growth, metastasis, and apoptosis." (PMID 40109856, 2025). "FASN inhibitors are particularly effective against cancers with dysregulated lipid metabolism, and target multiple anabolic and oncogenic signaling pathways." (PMID 39757995, 2025). "Similar to FASN, elevated levels of CTP are associated with tumor growth and invasion in various cancer cell lines." (PMID 41421797, 2025). "Since the ascription of an oncogenic role for FASN, this enzyme has been considered a potential therapeutic target for cancer treatment." (PMID 40149683, 2025). "Our prior studies and those of others have documented that FASN inhibitors induce apoptosis selectively in cancer cells with elevated FASN expression." (PMID 40733158, 2025). "PAX2 regulates the expression of key enzymes in fatty acid synthesis, such as FASN (Fatty Acid Synthase), which is commonly overexpressed in cancers." (PMID 40506992, 2025). "FASN inhibition disrupts membrane synthesis, survival signaling, and energy homeostasis, making it a promising metabolic target for cancer treatment." (PMID 40735642, 2025). "FASN, a key gene in mediating fatty acid metabolism, also exhibited high expression levels in primary cancer samples and CRPC samples, with values of 0.6295 and 0.6141, respectively, compared to 0.1640 in normal samples." (PMID 39988626, 2025). "While FASN expression is low in normal cells due to sufficient dietary fat intake, it is upregulated in cancer cells to support rapid growth and membrane synthesis." (PMID 40869407, 2025). "Consistent with earlier findings showing that resveratrol suppresses FASN expression in SK-BR-3 cells, our study confirms this effect and further extends the understanding of its anti-cancer action." (PMID 40733158, 2025). "In GC, FASN overexpression has been consistently reported in cancer tissues compared to adjacent normal mucosa." (PMID 41154605, 2025).
cancer (continued). "Lipid metabolism is recognized as a crucial pathway in cancer, with FASN serving as the central regulatory factor." (PMID 40764609, 2025). "The changes in FASN activity are considered the stress response of cancer cells reacting to changes in TMEs and have been identified as a significant contributor to the proliferation, metastasis, and progression of cancer." (PMID 40709184, 2025). "Dysregulation of lipid metabolic enzymes, such as fatty acid synthase (FASN) and acyl-CoA oxidase 1, results in lipid metabolism reprogramming in cancers." (PMID 40148316, 2025). "Reprogramming of lipid metabolism in cancer-associated fibroblasts was shown to enhance CRC cell migration, and overexpression of FASN in CRC cells increases O-GlcNAcylation of proteins, promoting tumor growth and survival." (PMID 40942159, 2025). "DHA, for example, significantly reduces fatty acid synthase (FASN) expression in cancer cells, inhibiting ZDHHC5 activity and promoting the degradation of PD-L1 via the CSN5-dependent ubiquitin-proteasome pathway." (PMID 40180214, 2025). "Numerous enzymes associated with de novo FA synthesis, such as FASN, ACC, and SCD, are frequently overexpressed in various cancers, thereby boosting FA production and contributing to the malignancy of these tumors." (PMID 39425259, 2025). "Elevated HER2 expression activates FASN activity, fostering cancer cell proliferation, while FASN amplifies the HER2-mediated signaling pathway." (PMID 40303293, 2025). "In cancer, enzymes like fatty acid synthase (FASN) and acetyl-CoA carboxylase (ACC) are often overexpressed, driving rapid cell proliferation and tumor growth." (PMID 40356601, 2025). "Fatty acid synthase (FASN) is a multifunctional peptidase that is highly expressed in many cancers, supporting cancer cell growth and proliferation and correlating with aggressive capacity." (PMID 40109856, 2025). "Overexpression and increased FASN activity have indeed been observed in cancer cells, suggesting that fatty acids can be utilized for cell replication." (PMID 39657036, 2025). "FASN, the rate-limiting enzyme in the fatty acid synthesis pathway, has also been widely reported to promote cancer progression." (PMID 40002387, 2025). "As the pivotal enzyme driving de novo lipogenesis, FASN enables the heightened lipid biosynthesis that cancer cells critically depend on to fuel their rapid proliferation, a metabolic adaptation absent in normal cellular physiology." (PMID 40466438, 2025). "FASN, the rate-limiting enzyme in de novo lipogenesis, is often upregulated in cancer, providing growth and survival advantages across various malignancies, including PCa 200-203." (PMID 40521202, 2025). "There are also ongoing clinical trials exploring the efficacy of FASN inhibitors in combination with other therapies for cancers like ovarian cancer." (PMID 40901481, 2025). "Owing to the role of nutrient-sensing of O-GlcNAcylation, our findings align with previous reports highlighting FASN O-GlcNAcylation as a modification that promotes cancer cell survival during starvation." (PMID 40684943, 2025). "Inhibition of FASN resulted in the decrease of lipogenesis, self‐renewal ability and chemotherapy resistance in the cancer cells." (PMID 40621620, 2025). "FASN, a key enzyme in many cancers, positively correlates with cancer progression, drug resistance, and HER2 positivity rate in patients with BC." (PMID 40548063, 2025). "In healthy cells, de novo fatty acid synthesis (FAS) largely depends on extracellular uptake, while in cancer cells, this process is markedly amplified, predominantly driven by the enzyme fatty acid synthase (FASN)." (PMID 41164182, 2025). "Altogether, these data highlight the complex relationship between FASN and O-GlcNAcylation in cancer cells." (PMID 40684943, 2025).
cancer (continued). "Inhibiting FASN to block de novo palmitate synthesis offers a biologically plausible approach to cancer therapy." (PMID 41009695, 2025). "Compared to normal tissues, FASN expression in cancer tissues and adjacent non‐cancerous tissues was markedly stronger." (PMID 40995612, 2025). "Fatty acid synthase (FASN) is one of the key enzymes involved in lipogenesis, which is a common metabolic pathway altered in cancer cells." (PMID 40643470, 2025). "In terms of clinical relevance, targeting FASN has shown great potential in preclinical studies for various cancers." (PMID 40901481, 2025). "Both ACC and FASN are commonly upregulated in various cancer types, and FASN has been recognized as a promising therapeutic target." (PMID 40552664, 2025). "Given the increased sensitivity of KAR cells to FASN inhibition in vitro, we investigated the anti‐cancer effects of TVB‐2640 in vivo in KAR mice." (PMID 40621620, 2025). "FASN is involved in different hallmarks of cancer, which strongly emphasizes its pro-oncogenic nature." (PMID 40684943, 2025). "In The Cancer Genome Atlas (TCGA) database, the expression of FASN was greater in CRC patients compared to other key enzyme-encoding genes." (PMID 40148316, 2025). "FASN exhibits low expression in quiescent normal cells, but is overexpressed in many types of cancer." (PMID 39925801, 2025). "Several genes altered during activation are approved or potential drug targets, including HMGCR, FADS1/2 and CPT1A, while others, such as FASN, CD36, and CTSD, are directly implicated in cancer-related processes." (PMID 40759959, 2025). "In certain cancer cells, FASN has been shown to indirectly regulate the Wnt/β-catenin signaling pathway." (PMID 39567194, 2025). "USP13 interacts with FASN to enhance its protein stability to promote fatty acid synthesis, cancer stemness and sphere formation." (PMID 40621620, 2025). "FASN, one of the lipogenic enzymes, has been known for many years to be upregulated in several cancer types, including DLBCL." (PMID 40149683, 2025). "Cancer cells enhance de novo lipid synthesis by fatty acid synthase (FASN), supporting their growth and damaging the function of dendritic cells." (PMID 41236698, 2025). "This process is often associated with hypoxia in tumor cells, and HIF-1α induces the production of fatty acid synthase in cancer cells, thus shifting the metabolism from glucose metabolism and acetyl coenzyme A to lipid metabolism." (PMID 40696413, 2025). "Inhibition of FASN has demonstrated the ability to arrest PCa growth both in vitro and in vivo and shown promise in targeted cancer therapy." (PMID 39973042, 2025). "Fatty acid synthase (FASN) is a key enzyme of de novo lipogenesis that plays critical roles in cancer cell proliferation and lipid metabolism." (PMID 40643470, 2025). "When hypomethylated, RAC3 can promote cell proliferation and invasion by increasing FASN expression in EC, potentially serving as a link between these two cancer types." (PMID 40564925, 2025). "While therapeutic strategies such as FASN inhibition or ACLY/SCD1 synthetic lethality have shown promise in other cancers, the lipid metabolic dependencies specific to CCA remain largely unexplored." (PMID 41291880, 2025). "Currently, TVB-2640, a second-generation targeted drug for FASN, has entered the phase 2 clinical trial stage and has been confirmed to have safe and effective cancer inhibitory effects." (PMID 39984452, 2025). "Meanwhile, FASN has arguably received the most widespread interest in terms of cancer therapies targeting dysregulated lipid metabolism." (PMID 40814339, 2025). "Dysregulated lipogenesis, driven by fatty acid synthase (FASN) overexpression, promotes tumour progression and is associated with poor clinical outcomes across multiple cancer types, including ovarian and other malignancies." (PMID 40308074, 2025). "The expression of FASN is highly upregulated in malignant tumors and provides energy for tumor cell proliferation." (PMID 40180937, 2025).
cancer (continued). "Fatty acid synthase (FASN) is notably overexpressed in CRC, which is closely associated with the invasive and metastatic abilities of cancer cells." (PMID 41031059, 2025). "On the contrary, high FASN expression was significantly correlated with poor tumour differentiation, high body mass index (BMI) and increased cancer cachexia." (PMID 40621620, 2025). "Inhibition of Fatty acid synthase (FASN) in combination with chemotherapy has been reported to increase the efficacy of these chemotherapy in treatment resistant cancers both in-vitro and in-vivo." (PMID 39965288, 2025). "Inhibition of FASN can induce cancer cell death through mechanisms such as membrane disruption, inhibition of DNA replication, accumulation of toxic malonyl-CoA, and suppression of anti-apoptotic proteins." (PMID 40942159, 2025). "This compound has also demonstrated anti-cancer activities in various preclinical models as a potent FASN inhibitor." (PMID 40263296, 2025). "FASN, the enzyme responsible for catalyzing the final steps of de novo fatty acid synthesis, is typically overexpressed in cancer cells but maintained at low levels in normal tissues." (PMID 40942159, 2025). "In contrast, FASN expression becomes overexpressed in cancer cells due to rapid growth and increased metabolic burden." (PMID 40133683, 2025). "FASN overexpression in malignancies correlates with poor prognosis, reflecting its essential role in maintaining cancer cell survival and proliferation." (PMID 40466438, 2025). "FASN is a key enzyme in adipogenesis and an important contributor to the progression of many metabolic disorders such as cancer, obesity, and NAFLD." (PMID 40432434, 2025). "Recently, the dysregulated lipidmetabolic‐related lncRNAs and circRNAs in cancers have been demonstrated to play key roles in regulating FASN expression by the ceRNA mechanism." (PMID 37939296, 2024). "Zeb1-binding regions were associated with an active, open (FADS2) or inactive, closed (SCD and FASN) chromatin state in Zeb1high-expressing cancer cells, and an inverse pattern in Zeb1-depleted cells." (PMID 39009641, 2024). "FASN catalyzes the “de novo” synthesis of fatty acids and is deregulated in several cancers, including GBM." (PMID 39590169, 2024). "Fatty acid synthesis enzymes, including ACC, FASN, and SCD, are upregulated in various cancers and are associated with cancer progression." (PMID 38610991, 2024). "We have previously reported that FASN inhibition can result in increased mitochondrial apoptosis priming, placing cancer cells in a primed-for-death state that is “addicted” to BCL-2 anti-apoptotic proteins." (PMID 39349429, 2024). "FASN, a well-studied de novo lipogenesis enzyme in cancer, plays a pivotal role in the synthesis of palmitate (C16:0) from acetyl-CoA and malonyl-CoA." (PMID 39551780, 2024). "Rhaponticin and desoxyrhaponticin can inhibit fatty acid synthase and are considered potential therapeutic agents to treat cancer." (PMID 38746013, 2024). "The FASN dependence of the cancer cell immune escape machinery was formally defined through mathematical modeling and mechanistic exploration of the experimental data." (PMID 39349429, 2024). "In contrast, inhibition of FASN by orlistat or C75 enhanced the effect of oxaliplatin in cancer cells." (PMID 39624081, 2024). "Although FASN expression remains low in most normal human tissues, it has been observed to be significantly elevated in several cancer types such as breast, prostate, colon and lung cancers." (PMID 38765144, 2024). "In our application, orlistat was found to inhibit cell proliferation, migration and invasion by specifically inhibiting FASN on CBR4 knockdown cells, and reversed the cancer‐promoting effect of FASN." (PMID 39524139, 2024). "TVB-2640 inhibits FASN and has also entered a phase I clinical trial of colon and other resectable cancers (NCT02980029)." (PMID 38287402, 2024).